RNU6-1102P (RNA, U6 small nuclear 1102, pseudogene)
Gene: Small nuclear RNA gene on chromosome 1 (78,088,988 to 78,089,083, reverse strand). Ensembl gene ENSG00000251958.
Homologues: Orthologues: chimpanzee U6 (100% identical), rabbit U6 (77% identical), dog U6 (76% identical), pig U6 (75% identical). Paralogues in human: RNU6-477P (81% identical), RNU6-1042P (80% identical), RNU6-1158P (80% identical), RNU6-166P (80% identical), RNU6-188P (80% identical), RNU6-361P (80% identical), RNU6-455P (80% identical), RNU6-474P (80% identical), RNU6-698P (80% identical), RNU6-831P (80% identical), RNU6-891P (80% identical), RNU6-949P (80% identical), and 1286 more.